KCNA10 (potassium voltage-gated channel subfamily A member 10)
Description:
Voltage-gated potassium ion channel that mediates K(+) permeability of excitable membranes. When opened in response to the voltage difference across the membrane, KCNA10 channel selectively allows the flow of potassium ions across the membrane down their electrochemical gradient.
Synonyms: Kv1.8; Kcn1
Tractability: Small molecule: an approved drug acts on it; it belongs to a druggable protein family. Antibody: its Gene Ontology location is reachable by antibodies, with high confidence; UniProt predicts a signal peptide or a membrane-spanning region.
Target class: Potassium channels; Ion channel; Voltage-gated ion channel; Voltage-gated potassium channel
Gene: Protein-coding gene on chromosome 1 (110,517,217 to 110,519,175, reverse strand). Ensembl gene ENSG00000143105.
Subcellular location: Membrane
Pathways (Reactome):
Neuronal System: Voltage gated Potassium channels
Gene Ontology:
Molecular function: protein binding; voltage-gated potassium channel activity; delayed rectifier potassium channel activity; intracellularly cyclic nucleotide-activated monoatomic cation channel activity; monoatomic ion channel activity
Biological process: potassium ion transport; action potential; potassium ion transmembrane transport; monoatomic ion transport; protein homooligomerization; transmembrane transport
Cellular component: membrane; plasma membrane; voltage-gated potassium channel complex
Genetic constraint (gnomAD): Loss-of-function variants: 17 observed, 24.8 expected, observed/expected ratio (o/e) 0.69, 90% interval 0.47 to 1.03. The upper end of that interval is the gene's LOEUF score, 1.03, which puts it in group 4 of 6, group 1 being the genes least tolerant of losing a copy. Missense variants: 677 observed, 683.95 expected, observed/expected ratio (o/e) 0.99, 90% interval 0.93 to 1.05. Synonymous variants: 276 observed, 259.51 expected, observed/expected ratio (o/e) 1.06, 90% interval 0.96 to 1.17.
Homologues: Orthologues: chimpanzee KCNA10 (99% identical), macaque KCNA10 (98% identical), guinea pig KCNA10 (95% identical), mouse Kcna10 (94% identical), pig KCNA10 (93% identical), rat Kcna10 (92% identical), dog KCNA10 (92% identical), tropical clawed frog kcna10 (68% identical). Paralogues in human: KCNA4 (59% identical), KCNA5 (59% identical), KCNA3 (59% identical), KCNA1 (58% identical), KCNA2 (58% identical), KCNA6 (57% identical), KCNA7 (52% identical), KCNC3 (34% identical), KCNC4 (34% identical), KCNC2 (34% identical), KCNB2 (33% identical), KCNC1 (33% identical), and 19 more.
Diseases named in the same sentence as KCNA10 in open-access papers:
KCNA10 is named in the same sentence as 12 diseases in open-access papers, as found by Europe PMC text mining. Sharing a sentence is not in itself a finding about the gene and the disease. The quoted sentences say what the papers report.
long QT syndrome (1 paper, 2025). "Very recently a missense mutation of KCNA10 has been involved in epinephrine provoked long QT syndrome with a familial history of sudden cardiac death." (PMID 40853747, 2025).
cancer (5 papers, 2012 to 2023). A tumor composed of atypical neoplastic, often pleomorphic cells that invade other tissues. "We evaluated the overall genetic alterations in all KCNA genes (KCNA1, KCNA2, KCNA3, KCNA4, KCNA5, KCNA6, KCNA7, KCNA10) using the TCGA Pan-Cancer Atlas dataset, collecting data from 32 human cancers (10,953 patients in total)." (PMID 36978819, 2023). "Furthermore, the roles of KCNA10 and ZNF705D in the pathogenesis of cancer, including OSCC, have not been investigated, implying the novel insights gained from this study and new avenues for the diagnosis of and new treatment strategies for OSCC." (PMID 34051764, 2021).
KCNA10 also shares sentences with these, for which no sentence is quoted: tumor (3 papers); pancreatic cancer (2); Anxiety (1); asthma (1); brain disorder (1); depression (1); glioma (1); hypothyroidism (1); melanoma (1); Parkinson’s (1).